IL6 (interleukin 6)
Diseases named in the same sentence as IL6 in open-access papers (continued):
Sharing a sentence is not in itself a finding about the gene and the disease.
liver fibrosis (continued). "It was already shown 20 years ago that IL6 deficiency causes enhanced liver fibrosis upon the development of liver injury." (PMID 34047814, 2021). "In the liver fibrosis caused by CCl4, the levels of mRNA encoding inflammatory factors F4/80, IL-6, IL-1β, and TNF-α reached a high value at 12 weeks." (PMID 33117360, 2020). "The significant associations of advanced liver fibrosis with higher levels of IL-6, IFN-γ, IL-10, and GM-CSF, despite being insignificant upon Bonferroni correction, are in accordance with some previous studies and are worthy of further investigation." (PMID 33348839, 2020). "Liver fibrosis is associated with upregulation of Tgf-β and biliary periductal fibrosis and increased levels of Il-6 characterize chronic opisthorchiasis." (PMID 29953446, 2018). "Inflammatory cytokines such as TNF-α, IL-6, and IL-1β are the main factors controlling the inflammatory response that causes liver damage and liver fibrosis." (PMID 28594374, 2017). "According to the network analysis, the IL-6 signaling pathway seemed to be involved in liver fibrosis caused by DMN." (PMID 29179490, 2017). "Hepatic fibrosis was increased in IL-6−/− mice and in IL-10−/− mice due to the loss of hepatocyte protection." (PMID 22973518, 2012). "Our study provides novel insights into how myeloid-specific Tet2 deficiency exacerbates liver fibrosis through the Ccl2/Ccl8–pMDMs–IL-6–HSCs axis, offering a potential therapeutic avenue for targeting fibrosis in populations with abundant aging individuals with TET2 mutations." (PMID 41474968, 2026). "TNF-α, IL-6, and interleukin-1 beta (IL-1β) are proinflammatory cytokines that work in a vicious cycle with NF-κB signaling pathways to promote one another and intensify the inflammatory response, causing liver fibrosis." (PMID 40552161, 2025). "In addition, self-administration of CCl4 (Sham + CCl4 and PINX + CCl4 groups) to induce liver fibrosis caused a significant increase in the liver levels of IL-1β and IL-6 (p < 0.001) compared to the control and sham." (PMID 39007940, 2025). "Lastly, myeloid-specific IL-6 signaling has been implicated in liver fibrosis regulation." (PMID 40668532, 2025). "IL-6 plays an important role in liver fibrosis caused by various etiologies." (PMID 39995661, 2025). "The complex role of IL-6 in liver disease is associated with increased susceptibility to liver damage, stimulation of hepatocyte apoptosis, and promotion of insulin resistance, thereby contributing to the development of liver fibrosis." (PMID 38116551, 2023). "As SOCS1 was initially discovered as a negative regulator of the inflammatory cytokine IL-6 signaling, loss of SOCS1 could amplify IL-6 signaling and promote liver fibrosis." (PMID 37860002, 2023). "Hepatic fibrosis induced by carbon tetrachloride has been promoted in IL-6-deficient mice." (PMID 32121064, 2020). "Previous studies have shown that the antifibrosis effect of a type of ginsenoside AD-2 extracted from ginseng on thioacetamide-induced liver injury in mice is related to the inflammatory factors (including TNF-α, IL-1β, caspase-1, and IL-6) associated with hepatic fibrosis." (PMID 32724321, 2020). "Furthermore, both TIMP1 and SLPI are induced by IL-6 as shown by studies on the pathogenesis of liver fibrosis and inflammation caused by innate immunity." (PMID 31404090, 2019). "A second potential biomarker, IL-6, has been associated with the development of hepatic fibrosis." (PMID 29149171, 2017). "Thus, while IL-6 triggers proinflammatory responses in macrophages, IL-10 mediates anti-inflammatory responses that are associated with decreased liver fibrosis." (PMID 22973518, 2012). "Our findings extend this understanding by identifying Tet2−/− pMDMs as a key source of IL-6 in liver fibrosis." (PMID 41474968, 2026).
liver fibrosis (continued). "In conclusion, Tet2ΔMye-induced myeloid hematopoiesis exacerbates liver fibrosis in both young and aging mice through a consistent Ccl2/Ccl8–pMDMs–IL-6–HSCs pathway highlighting a unified therapeutic target for age-associated fibrosis." (PMID 41474968, 2026). "For example, blocking IL‐6 via disrupting the HLF/IL‐6/STAT3 circuit has been associated with reduced HSCs induction and improved liver function in experimental models of liver fibrosis." (PMID 41487942, 2026). "For instance, interleukin-6 (IL-6) has been shown to mediate the transition from liver fibrosis to cirrhosis by promoting inflammation and HSC proliferation." (PMID 40806358, 2025). "Adipokine pathways and inflammatory markers like adiponectin, leptin, and IL-6 are the focus of the green cluster, which is closely related to histological evaluations of cirrhosis and hepatic fibrosis." (PMID 40868109, 2025). "The bioinformatics analysis indicated that TNF, IL-6, PPARG and MMP9 were promising candidate genes that can serve as diagnostic and prognostic biomarkers for liver fibrosis." (PMID 39869574, 2025). "M1 macrophages represent high expression of CD86, CD68, and iNOS, and secrete the pro-inflammatory factors such as TNF-α, IL-6, and ROS, that exacerbate the hepatic inflammation and tissue injury and promote the development of hepatic fibrosis." (PMID 41375167, 2025). "IL-17A has been shown to stimulate the activation of HSCs and contribute to liver fibrosis by increasing the expression of pro-inflammatory cytokines, such as IL-6, IL-1β, and TNF-α, as well as pro-fibrotic factors like TGF-β and α-SMA." (PMID 39995661, 2025). "MiR-34a promotes the expression of transforming growth factor-beta type 1 receptor (TβR1), TGF-β1 and p-SMAD2/3, which are connected to liver fibrosis and inflammatory cytokines such as interleukin-6 (IL-6) and IL-7." (PMID 40801570, 2025). "This activation leads to the secretion of inflammatory mediators, such as interleukin-6 (IL-6) and senescence-associated secretory phenotype (SASP) factors, which collectively contribute to liver fibrosis and the progression to HCC." (PMID 41049851, 2025). "Correspondingly, IL-6 protein levels are markedly higher in cirrhosis patients compared to those with liver fibrosis." (PMID 39995661, 2025). "Initially, through network pharmacology, we predicted that the top three key proteins targeted by YQHX in alleviating liver fibrosis were IL-1β, IL-6, and TNF-α." (PMID 41296792, 2025). "As a key pathway in fibrosis development, the IL-6-related signaling cascade holds promise as a novel serum marker for evaluating the severity of liver fibrosis." (PMID 39995661, 2025). "Numerous studies have demonstrated that, in addition to promoting inflammatory responses, IL-6 induces lymphocyte differentiation and proliferation, facilitates HSCs activation, and contributes to the development of liver fibrosis." (PMID 39995661, 2025). "CCl4 triggers an inflammatory response in the liver by increasing the production of inflammatory factors such as tumor necrosis factor (TNF), interleukin (IL)-1β, and IL-6, which are essential to liver fibrosis." (PMID 39968080, 2025). "We evaluated the following indicators by immunohistochemical staining to evaluate the degree of inflammation during liver fibrosis: IL-1β, IL-6, Antigen Ki67, and TNF-α." (PMID 40143016, 2025). "Specifically, 680 proteins in cluster 1, including pro- and anti-inflammatory cytokines (e.g., IL-6 and IL-10) and liver fibrosis markers (e.g., ACTA2, KRT19, and SPP1), increased progressively with fibrosis stages." (PMID 39889710, 2025). "Activated inflammatory cells in the liver, such as Kupffer cells and macrophages, release various pro-inflammatory cytokines, including tumor necrosis factor-alpha (TNF-α) and interleukin-6 (IL-6), which exacerbate hepatocyte damage and promote liver fibrosis." (PMID 40538532, 2025).
liver fibrosis (continued). "Significant differences were found in platelet count, liver enzymes (ALT, AST, GGTP, ALP), inflammatory markers (CRP, IL-6, IL-18), fibrinogen, and markers of liver fibrosis (APRI, FIB-4, ElastPQ)." (PMID 40806277, 2025). "This protective finding is also different to chronic hepatic injury models, such as CCl4-induced liver injury, where Sema7a promotes hepatic fibrosis and Il6 and Ccl2 expression." (PMID 40114253, 2025). "The levels of cytokines implicated in liver fibrosis, cirrhosis, or the initiation of HCC in HIV + participants were similar to those in HCC + participants with the exception of IL-6 and MCP-1." (PMID 41219858, 2025). "The activation of signal transducer and transcription factor 3 (STAT3) by IL-6 also correlates with liver fibrosis and hepatic stellate cell activation." (PMID 39968080, 2025). "PZW alleviated hepatic fibrosis in vivo, primarily by inhibiting collagen accumulation through navigating IL-6/JAK2/STAT3 and TGF-β/Smad2/3 signaling pathways." (PMID 41293246, 2025). "Previous studies have suggested that TCM or herbal remedies can decelerate liver fibrosis by modulating IL-6 levels in disease mouse models." (PMID 41296792, 2025). "The isolated hepatocytes were then treated with recombinant mouse IL-6 to mimic the inflammatory environment characteristic of liver fibrosis." (PMID 40789837, 2025). "In a hyperglycemic state, the release of inflammatory factors such as IL-6, TNF-α, IL-8, and IL-1β can activate hepatic stellate cells and Kupffer cells, causing liver fibrosis, and can also stimulate cardiac fibroblasts, exacerbating myocardial fibrosis." (PMID 39775020, 2024). "Our current study confirmed the anti-inflammatory effects of vitamin D supplementation on mice with liver fibrosis through reductions in IL-1β, IL-4, IL-6, and TNFα in addition to OPN." (PMID 39654627, 2024). "A clear pattern appeared when the full set of results was taken into consideration, with data converging towards an IL6/TGFβ-driven pathway responsible for the hepatic fibrosis development." (PMID 39144627, 2024). "AA did not exert the anti‐inflammatory effect as reported in rats with CCl4‐induced liver fibrosis that AA significantly reduced hepatic mRNA expression of Il1b, Il6, and Tnfa." (PMID 39501714, 2024). "HSCs are pivotal in liver fibrosis, undergoing transformation into myofibroblasts and regulated by key mediators like IL-6 and TGF-β." (PMID 38715844, 2024). "IL-4 and IL-6 protect against hepatic fibrosis, IL-4 through secretion of matrix metalloproteinase-12 (MMP-12), and IL-6 through the promotion of proliferation/survival of HSCs." (PMID 38251375, 2024). "Earlier studies showed a good correlation between cytokine levels and fibrosis stages; higher levels of IL-6 and TNF-α were associated with the presence of advanced liver fibrosis." (PMID 39272729, 2024). "The ethanol extracts of aerial parts exhibited potent hepatoprotective effects by significantly suppressing TNF-α and IL-6 levels in thioacetamide (TAA)-induced liver fibrosis in rats, thus restoring liver function." (PMID 38310564, 2024). "Because inflammatory cytokines play crucial roles in the development and progression of hepatic fibrosis, we quantified IL-1β, IL-6, and TNF-α levels using ELISA kits." (PMID 38434258, 2024). "Remarkably, the liver fibrosis mice treated with vitamin D resulted in a substantial reduction in the levels of the tested cytokines: IL-1β (2.2-fold), IL-4 (1.9-fold), IL-6 (8-fold), OPN (1.45-fold), and TNF-α (1.7-fold) compared to CCl4 alone." (PMID 39654627, 2024). "In the context of HCV, IL-6 has been shown to play a significant role in the viral persistence/progression of liver fibrosis." (PMID 39336572, 2024). "The vitamin E also plays a critical role in regulating the inflammatory response by inhibiting the expressions of IL‐1β, MCP and IL‐6, thus attenuating liver fibrosis." (PMID 38652023, 2024).
liver fibrosis (continued). "To elucidate the immunosuppressive capabilities of MSC-CM within the liver fibrosis, we examined the expression of two crucial inflammatory mediators, IL-6 and IL-8 in HSCs." (PMID 38874773, 2024). "Considering the important potential of IL-6 in HSC activation, our findings provide mechanistic and translational insights into the causative role of Fendrr in promoting HSC activation and liver fibrosis." (PMID 38762176, 2024). "When examining the role of Fendrr in liver fibrosis, we found that the upregulation of Fendrr promoted IL-6 production and secretion from hepatocytes." (PMID 38762176, 2024). "When produced persistently, elevated levels of interleukin-6 (IL-6) in cirrhotic patients contribute to ongoing inflammation and tissue damage such as liver fibrosis." (PMID 38894778, 2024). "Collectively, these findings suggested that the causal role of Fendrr in liver fibrosis is associated with its interaction with STAT2, which promotes the induction of IL-6 and activation of HSC in a paracrine manner." (PMID 38762176, 2024). "After suffering from liver fibrosis, the levels of IL-1β and IL-6 in the liver were significantly increased (p < 0.001 vs. control group)." (PMID 39195542, 2024). "As expected, the ectopic expression of STAT2-Mut1 abolished the Fendrr-mediated increase of serum IL-6 in CCl4-treated mice and greatly suppressed the profibrotic effect of Fendrr on liver fibrosis." (PMID 38762176, 2024). "In our included research literatures, the hepatic fibrosis models for A/G, Collagen III, and PDGF-BB immunohistochemistry results were all rats, while the hepatic fibrosis models for IL-6 were all mice." (PMID 38781262, 2024). "A number of studies have demonstrated that IL-6 and IL-1β play a crucial role in the progression of steatosis to steatohepatitis and liver fibrosis." (PMID 37504922, 2023). "Together, these data evinced that the down-regulated PGC-1α expression by I/R was associated with hepatic macrophage polarization toward M2-type and liver fibrosis in mice by enhancing the IL-6/STAT3 signaling." (PMID 37679346, 2023). "More importantly, administration with AAV8-PGC-1α rescued the I/R-induced liver fibrosis by inhibiting the IL-6/JAK2/STAT3 signaling and M2-type macrophage polarization in the liver." (PMID 37679346, 2023). "The observed common canonical pathways were molecular mechanisms of cancer, NAFLD signaling pathway, hepatic fibrosis signaling, IL-6 signaling, and estrogen receptor signaling in the blood tissue." (PMID 38068980, 2023). "IL-6 and IL-8 were increased in hamster and human with hepatobiliary abnormalities.Treatment with progranulin showed decreasing of liver fibrosis and inflammation in mice and macrophage." (PMID 36993607, 2023). "Activation of the TLR4-myD88-NFκB signaling pathway, an important pathway associated with hepatic fibrosis and HCC, can lead to the release of downstream inflammatory factors and induce the production of IL-1, IL-6, and TNF-α." (PMID 38074679, 2023). "Oxymatrine reduces liver fibrosis by limiting the pro-inflammatory cytokines, interleukin-6 and TNF-α generated by carbon tetrachloride and boosting anti-inflammatory factors such as interleukin-10." (PMID 36985782, 2023). "It seemed that different factors were responsible for the MPV increase in NASH subjects with liver fibrosis, such as insulin resistance and AT-related proinflammatory cytokines (including IL-1β, IL-6 and TNFα)." (PMID 36768637, 2023). "Untreated STZ/HFD-exposed mice displayed significant increases in NAFLD activity scores, liver triglycerides, NAMPT hepatic expression, plasma cytokine levels (eNAMPT, IL-6, and TNFα), and histologic evidence of hepatocyte ballooning and hepatic fibrosis." (PMID 36809677, 2023). "Studies have demonstrated that TNF-α upregulates the expression of IL-6 in CCl4-induced liver fibrosis." (PMID 37111188, 2023).
liver fibrosis (continued). "Serum TNF-α, IL-1β, and IL-6 concentrations in mice with CCl4-induced liver fibrosis were increased in our study, which coincided with the assay results of inflammatory factors in previous studies." (PMID 38116381, 2023). "Previous studies have also suggested that IL6/STAT3 signaling was a promising target for treating liver fibrosis." (PMID 37860111, 2023). "SEMA3C regulates extracellular matrix composition through increased expression of IL-6, transforming growth factor-β (TGF-β) and connective tissue growth factor (CTGF), and was implicated in the development of liver fibrosis." (PMID 37893159, 2023). "Treatment with Arthrospira, a genus of free-floating filamentous cyanobacteria, increased serum IFN-γ levels but decreased serum TNF-α and IL-6 and hepatic fibrosis and steatosis in CHB patients receiving NA therapy." (PMID 37239062, 2023). "Exosomes can reduce liver fibrosis by inhibiting the production of inflammatory factors such as interleukin-6 (IL-6), interleukin-1β (IL-1β) and tumor necrosis factor-α (TNF-α) and pro-fibrotic transforming growth factor-β1 in Kupffer cells." (PMID 37006266, 2023). "The gene expression levels of TNF‐α, IL‐1β and IL‐6 are concomitantly increased, and one such inflammatory reaction has been suggested to play a major contribution to hepatic fibrosis and disruption of lipid metabolism." (PMID 37177862, 2023). "Evermore, several studies acknowledged a positive correlation between IL-6, liver fibrosis, and fatty liver changes." (PMID 37627620, 2023). "Compared to hepatic fibrosis and cardiac hypertrophy pathways, fewer DEGs are part of IL-6 and wound healing signaling networks." (PMID 36552714, 2022). "It is also known that the upregulation of IL-6 and subsequent STAT3 regulatory cascades promote hepatic stellate cell (HSC) activation, causing liver fibrosis and cirrhosis." (PMID 36498787, 2022). "A recent study corroborated our findings from another aspect where myeloid-specific IL-6 signaling inhibits liver fibrosis via exosomal transfer of antifibrotic miR-223 into hepatocytes, suggesting the protective role of IL-6 signaling in NAFLD." (PMID 35747747, 2022). "The results showed that FA inhibited the proliferation and migration of LX2 cells and adjusted the expression of MMP-1, TIMP-1, COLI, α-SMA, TNF-α, IL-6 and IL-1β as well as promoted collagen metabolism to show potential in anti-hepatic fibrosis." (PMID 35035671, 2022). "The IL6-treated rat liver showed increased collagen synthesis and severe liver cell necrosis, implying the involvement of IL-6 in the development of hepatitis and liver fibrosis." (PMID 35462928, 2022). "In a CCL4-induced rat liver fibrosis model, BM-MSCs treatment reduced IL-17, IL-2 and IL-6 serum proteins and downregulated IL-17A and IL-17RA proteins in liver tissues." (PMID 35895169, 2022). "IL-6 and TNF-α enhanced the release of TGF-β1 to activate HSCs and cause fibrosis, suggesting that TNF-α and TGF-β1 upregulation occurred prior to liver fibrosis induction." (PMID 35840761, 2022). "An HIV-infected patient cohort with alcoholism showed a substantial and significant correlation between IL-6 and liver fibrosis." (PMID 36405584, 2022). "In the same way, transplantation of HLCs eliminated CCl4-induced liver fibrosis and conserved the function of the liver via the release of transforming growth factors β 1, IL-6, and IL-10." (PMID 35765490, 2022). "A recent study demonstrated that loss of miR-200c accelerated intrahepatic inflammation and periductular fibrosis by targeting SESN1 and repressing the IL-6/AKT loop in cholestatic liver fibrosis models." (PMID 35662287, 2022). "Autophagy of LSEC also enables chemokines, inflammatory factors such as C-C chemokine ligand 2 (CCL2), C-C chemokine ligand 2 (CCL5), and interleukin-6 (IL-6) are enhanced, promoting the hepatic inflammatory response and thus liver fibrosis." (PMID 35529927, 2022).